RPL13AP3 (ribosomal protein L13a pseudogene 3 )
Synonyms: RPL13A_11_1370
Gene: Long non-coding RNA gene on chromosome 14 (55,766,245 to 55,767,717, forward strand). Ensembl gene ENSG00000293056.
Diseases named in the same sentence as RPL13AP3 in open-access papers:
RPL13AP3 is named in the same sentence as 1 disease in open-access papers, as found by Europe PMC text mining. Sharing a sentence is not in itself a finding about the gene and the disease.
RPL13AP3 shares sentences with these, for which no sentence is quoted: ovarian carcinoma (1 paper).